OR5J2 (olfactory receptor family 5 subfamily J member 2)
Description:
Odorant receptor.
Synonyms: OR11-266
Tractability: Antibody: UniProt places it where antibodies can reach, with medium confidence; UniProt predicts a signal peptide or a membrane-spanning region; its Gene Ontology location is reachable by antibodies, with medium confidence.
Gene: Protein-coding gene on chromosome 11 (56,176,618 to 56,177,556, forward strand). Ensembl gene ENSG00000174957.
Subcellular location: Cell membrane
Pathways (Reactome):
Sensory Perception: Expression and translocation of olfactory receptors
Gene Ontology:
Molecular function: odorant binding; olfactory receptor activity; G protein-coupled receptor activity
Biological process: sensory perception of smell; detection of chemical stimulus involved in sensory perception of smell; G protein-coupled receptor signaling pathway
Cellular component: plasma membrane; membrane
Genetic constraint (gnomAD): Loss-of-function variants: 4 observed, 7.41 expected, observed/expected ratio (o/e) 0.54, 90% interval 0.26 to 1.23. That is too few expected variants to judge how well the gene tolerates losing a copy. Missense variants: 410 observed, 374.44 expected, observed/expected ratio (o/e) 1.1, 90% interval 1.01 to 1.19. Synonymous variants: 171 observed, 144.96 expected, observed/expected ratio (o/e) 1.18, 90% interval 1.04 to 1.34.
Homologues: Orthologues: chimpanzee OR5J2 (97% identical), dog OR5J2 (82% identical), mouse Or5j3 (78% identical), dog OR5J2B (78% identical). Paralogues in human: OR5D18 (54% identical), OR5W2 (54% identical), OR5AP2 (54% identical), OR8U1 (54% identical), OR5B12 (53% identical), OR5C1 (53% identical), OR5I1 (52% identical), OR5L1 (52% identical), OR5L2 (51% identical), OR8D1 (51% identical), OR8U3 (51% identical), OR5B21 (51% identical), and 84 more.